VHL (von Hippel-Lindau tumor suppressor)
Diseases named in the same sentence as VHL in open-access papers (continued):
Sharing a sentence is not in itself a finding about the gene and the disease.
glioma (20 papers, 2011 to 2025). A benign or malignant brain and spinal cord tumor that arises from glial cells (astrocytes, oligodendrocytes, ependymal cells). "Using protein lysates extracted from our PB-Ras model of glioma, we found that Daam2 co-immunoprecipitates with VHL (and vice versa), suggesting that these proteins associate." (PMID 29053101, 2017). "von Hippel-Lindau (VHL) disease is a rare hereditary tumor syndrome caused by VHL gene mutations that is characterized by heterogeneous phenotypes such as benign/malignant tumors of the central nervous system, retina, kidney, adrenal gland, and pancreas." (PMID 27439424, 2016). "Importantly, inactivating mutations in VHL are predominately found in ccRCC and are very rare in most other forms of cancer, including glioma." (PMID 29053101, 2017). "In this study, VH032 induces apoptosis of glioma cells and inhibits the metastatic activity of glioma cells by influencing the protein content of the VHL/HIF-1α/VEGF pathway." (PMID 41030787, 2025). "VH032 is a ligand for VHL, and to date, there have been few studies that elucidated the anti-glioma effect of VH032." (PMID 41030787, 2025). "Our results showed that the expression levels of FBXO22, HIF-1α, and VEGFA in high-grade gliomas were much higher than those in low-grade gliomas, while the expression level of VHL in high-grade gliomas was much lower than that in low-grade gliomas." (PMID 38519492, 2024). "As parenchymal tumors of the central nervous system, such as gliomas, can arise from NSCs, this VHL-HIF transcriptional mechanism is crucial in the development of parenchymal tumors of the central nervous system." (PMID 36835292, 2023). "The Daam2–VHL relationship was first discovered in gliomas, with Nedd4 being a key upstream regulator of VHL." (PMID 36835292, 2023). "Simultaneously, we found that ITGB4 interacted with KLF4 and decreased its binding to the E3 ligase VHL in glioma cells, which subsequently enhanced KLF4 stability and increased KLF4 expression." (PMID 30658712, 2019). "Studies in glioma cell lines suggest that ID2 interference with VHL activity can deregulate HIF1α expression and promote tumorigenesis in xenograft models." (PMID 29053101, 2017). "Next, we extended these studies to our mouse models of glioma, finding that combined overexpression of VHL with Daam2 similarly suppressed the accelerated rate of tumorigenesis and proliferation mediated by Daam2-alone." (PMID 29053101, 2017). "Together, these studies represent the initial characterization of Daam2 function in glioma and define, for the first time, an upstream regulatory mechanism that controls VHL protein expression in cancer." (PMID 29053101, 2017). "(C–F) Representative immunohistochemical analysis of VHL expression in CRISPR-IUE glioma tumors derived from Daam2-overexpression (D) or knockout of Daam2 (F) and associated controls." (PMID 29053101, 2017). "Protein expression screening identified an inverse correlation between Daam2 and VHL expression across a host of cancers, including glioma." (PMID 29053101, 2017). "Our mechanistic studies revealed that Daam2 promotes glioma tumorigenesis via suppression of VHL, a classic tumor suppressor that promotes HIF1α degradation and inhibits Akt activity." (PMID 29053101, 2017). "Put together, these data indicate that Daam2 promotes tumorigenesis by suppressing VHL expression in glioma." (PMID 29053101, 2017). "Given its role as the central regulator of HIF1α, surprisingly little is known about the regulatory biology surrounding VHL and its role in glioma formation." (PMID 29053101, 2017). "Cell proliferation and invasion activity were significantly inhibited in VHL-transfected glioma cells (48 h after transfection)." (PMID 24650032, 2014). "The relative luciferase level for the VHL gene was significantly higher in lenti-AS-566-infected glioma cells than in lenti-NC-infected controls, and Western blot analysis confirmed these findings." (PMID 24650032, 2014).
glioma (continued). "We then performed colony formation assays, invasion assays and flow cytometry in VHL plasmid-transfected glioma cells." (PMID 24650032, 2014). "VHL was shown to be involved in the tumorigenesis of glioma, and we found that the 3’ UTR of VHL contained 2 potential complimentary binding sites for miR-566." (PMID 24650032, 2014). "Western blot analysis demonstrated that VHL protein expression was significantly increased in lenti-AS-566-infected glioma cells." (PMID 24650032, 2014). "The results of the present study revealed that VH032 plays a crucial role in antitumour effects on glioma cells in vitro by inhibiting the VHL/HIF-1α/VEGF signalling pathway and interfering with the proliferation, invasion, migration, apoptosis and cycle distribution of glioma cells." (PMID 41030787, 2025). "Interestingly, when ITGB4 levels were increased, it was able to interact with KLF4 and thus decrease its binding to the E3 ligase VHL, leading to its accumulation in glioma." (PMID 30658712, 2019). "Indeed recent studies in glioma have shown that ID2 can interfere with VHL activity in cell lines and that it’s subject to regulation by microRNAs." (PMID 29053101, 2017). "The RPPA data suggests that Daam2 modulates expression of VHL in glioma." (PMID 29053101, 2017). "G1 cell cycle arrest was induced and apoptosis was increased in VHL-transfected glioma cells." (PMID 24650032, 2014). "However, research on the impact of the VHL gene on human gliomas remains limited." (PMID 41030787, 2025). "Finally, we wanted to explore the clinical significance of FBXO22 and VHL functions in glioma." (PMID 38519492, 2024). "However, little is still unknown about the role of VHL in gliomas." (PMID 41030787, 2025). "The expression of FBXO22, VHL, HIF-1α, and VEGFA was detected by IHC staining using anti-FBXO22, VHL, HIF-1α, and VEGFA antibodies in the tissue sections of glioma patients." (PMID 38519492, 2024). "In contrast, in glioma stem cells, one of the human HIF−1 homologs, HIF-2α/EPAS1, is inhibited by DYRK1A/B in a VHL-dependent manner." (PMID 28562327, 2017). "In the present study, we confirmed that miR-566 was upregulated in human glioma cells, and repressing miR-566 could inactivate the EGFR pathway largely by targeting VHL." (PMID 24650032, 2014). "In addition, our data confirm that there are positive correlations among FBXO22, HIF-1α, and VEGFA expression, and there is a negative correlation between FBXO22 and VHL protein expression in glioma patients." (PMID 38519492, 2024).
metastatic disease (20 papers, 2015 to 2025). "Three criteria have been proposed to predict metastatic disease due to a p-NET in VHL: tumor size ≥ 3cm, exon 3 mutation, and growth capacity of the tumor (doubling time <500 days)." (PMID 40918781, 2025). "While two patients had additional pathogenic VHL or FH variants, these have been described to have a lesser impact on metastatic disease." (PMID 39351526, 2024). "As a result, it seems that the size of the primary VHL, pNET, and the risk of metastatic disease are related." (PMID 37251595, 2023). "The algorithm for genetic testing did not fit in 3 out of the 24 patients with hereditary disease as we observed one case of metastatic disease (arteria renalis invasion) in a patient with a VHL mutation and positive SDHB staining in 2 SDHD-related PPGL." (PMID 37434651, 2023). "A maximum renal mass diameter greater than 3 cm is associated with an increased risk of metastatic disease, although VHL-related ccRCCs tend to have limited local invasiveness and histologic grade." (PMID 36358771, 2022). "The sensitivities to the different imaging modalities depend on the presence of PGL versus PCC, HN PGLs, sporadic metastatic, or non-metastatic disease, cluster 1 Krebs cycle-related SDHx mutations and VHL/EPAS1 pseudohypoxia-related mutations or cluster 2 kinase signaling-associated mutations." (PMID 31597347, 2019). "In the European-American-Asian-VHL-PNEN-registry, comprising 273 patients with vPNEN, metastatic disease was found in 20% of cases, while a much lower risk was reported in other cohorts, ranging between 4.5 and 8.3% of cases." (PMID 36980625, 2023). "Metastatic disease is one of the features that indicates likelihood of a hereditary cause, and it is recommended that patients with malignant PCC should undergo genetic testing for SDHB, SDHC, SDHD, VHL and MAX." (PMID 29768630, 2018). "However, since all patients with ATRX variants presented with aggressive/metastatic disease despite initially presenting with PCC (low metastatic risk) and VHL or FH variants (low-moderate metastatic risk), we speculate, as others, that ATRX variants contribute to metastatic risk." (PMID 39351526, 2024). "With the discovery of VHL, the biology of the tumorigenesis of the syndrome was further evaluated, with implications for potential management of the not only VHL but also other forms of hereditary RCC and sporadic tumors in both localized and metastatic disease." (PMID 36421797, 2022). "In an older series of 52 PHEOs/PGLs patients (and n = 2 with VHL, one with nonmetastatic and one with metastatic disease), PET with 18F-DOPA and 18F-FDA had showed the same lesions; both were better than 123I-MIBG in imaging the patient with metastatic disease." (PMID 28890865, 2017).
lung carcinoma (19 papers, 2011 to 2025). "While VHL mutation is crucial for constitutive HIF-1α activation in lung cancer, understanding how cancer cells activate HIF-1α in VHL wild-type cancers is a key research focus." (PMID 40691138, 2025). "VHL encodes von Hippel-Lindau tumor suppressor and was shown to be hypermethylated in lung cancer." (PMID 24842468, 2014). "Multiple under-expressed proteins were also predictable to a great extent, the top-performing ones being CASP8, MET, BCL2, and SETD2 in BRCA; AR and TFRC in gastric cancer; and VHL in lung cancer with AUCs ranging 0.814–0.866." (PMID 38491101, 2024). "Using coimmunoprecipitation (co-IP) assays, TET3 was shown to form protein complexes with VHL in H1299 cells (a human lung cancer cell line) where VHL overexpression accelerated TET3 degradation." (PMID 39141428, 2024). "It has been found that knockdown of VHL inhibits tumor progression in lung carcinoma; it remains to be established if this is mediated by YAP1-dependent mechanisms." (PMID 35937460, 2022). "For example, three colon cancer tissues were separated from the others and grouped together with lung cancers, showing hypermethylation in the VHL and PRDM15." (PMID 24842468, 2014). "Moreover, siRNA mediated knockdown of FH has been shown to increase HIF-1α levels in A549 lung carcinoma cells which express VHL." (PMID 21695080, 2011). "In the present study, some of the mostly connected mRNAs were already reported to be correlated with lung cancer, including SOX2, FOXF1, PTK2B and VHL." (PMID 26159226, 2015). "In addition, SETD2 is mutated in other cancer types, such as non‐small cell lung cancer, where VHL and PBRM1 mutations rarely occur, although this does not preclude the possibility that SETD2 cooperates with other mutated genes such as K‐RAS in context of lung cancer." (PMID 37418588, 2024). "Similar findings were observed in VHL-positive CAKI-1 ccRCC and A549 lung cancer, suggesting that SphK1 activity regulates HIF-2α content regardless of the presence or absence of VHL." (PMID 26974204, 2016).
colon carcinoma (18 papers, 2014 to 2025). "Next, to establish proof of concept, we reconstituted VHL-deficient RKO colon carcinoma cells (VHL-/-), with the corresponding variant library." (PMID 36329119, 2023). "In conclusion, our results validate the role of the KynA/P4HA2/VHL/HIF-1α/HILPDA axis in promoting colon cancer progression due to sleep deprivation." (PMID 39920992, 2025). "To investigate the presence of KynA/P4HA2/VHL/HIF-1α/HILPDA axis in mediating the effects of sleep deprivation on colon cancer, we underwent rescue experiments." (PMID 39920992, 2025). "Here, we report a very rare case of tumor-to-tumor metastasis in a VHL patient whose colon cancer metastasized to the interior of a PNET and was detected during surveillance imaging." (PMID 35951216, 2022). "In conclusion, this report describes a very rare case of tumor-to-tumor metastasis in a VHL patient whose colon cancer metastasized to the interior of a PNET." (PMID 35951216, 2022). "Here, we report a case of tumor-to-tumor metastasis in a VHL patient in whom colon cancer metastasized to the interior of a PNET." (PMID 35951216, 2022). "Exosomal miR-21-5p released by colon cancer cells inhibited VHL expression in Schwann cells, which in turn stabilized the HIF-1α protein and increased the transcription of NGF." (PMID 36522730, 2022). "Furthermore, we used GEO dataset GSE10950 and tissue chips to assess P4HA2/VHL/HIF-1α/HILPDA signaling axis on colon cancer." (PMID 39920992, 2025). "Furthermore, miR-155-5p influences hypoxia by targeting VHL mRNA and its overexpression is additionally connected to diminished drug response and chemo- and radio-resistance of breast and colon cancer cells." (PMID 33535553, 2021). "Among cancers cells shown to express functional EpoRs include human breast carcinoma (MCF-7), hepatoma (HepG2), osteosarcoma (U2–OS), cervical carcinoma (HeLa), VHL-deficient renal clear cell carcinoma (RCC4), colon carcinoma (HCT-116), and colon carcinoma (7860-WT and SW480) cell lines." (PMID 31291309, 2019). "For example, HIF1-α activates p21 transcription, which blocks the interaction between VHL and HIF1 α, then inhibits the interpretation of HIF1 α, forms a positive feedback regulatory loop, and finally promotes cell growth of colon cancer." (PMID 35652045, 2022). "The increase of HIF-1α expression under hypoxia was reported to be inhibited by LW6 through the overexpression of VHL, leading to the inhibition of tumor angiogenesis in the HCT116 human colon cancer cell line." (PMID 26017562, 2015). "The usage of LW6 in the colon cancer cells has been shown to promote the degradation of HIF‐1α by upregulation of VHL without affecting HIF‐1β expression, giving rise to competent anti‐tumor efficacy in vivo." (PMID 37334735, 2023). "Notably, we observed VHL and ELOB, which are thought to form a protein complex, are top hits that are more essential in KRAS-mutant male colon cancer cells." (PMID 34663427, 2021). "Interestingly, a study comparing VHL and CRBN dependencies in diverse tumor types concluded that VHL-based PROTACs can induce degradation in a broader number of cell lines, as CRBN was frequently found inactivated or expressed at low levels in lung and colon cancer lines." (PMID 36765568, 2023).
melanoma (18 papers, 2011 to 2025). A malignant, usually aggressive tumor composed of atypical, neoplastic melanocytes. "First, the most prevalent driver mutations and pathway alterations driving carcinoma vary substantially by tissue (e.g., VHL loss in ccRCC vs. BRAFV600E mutations in melanoma)." (PMID 40238833, 2025). "Some genes were mostly restricted to certain subtypes; for example, BRAF mutations occurred mostly in melanoma, VHL mutations in kidney clear cell samples, and KEAP1 mutations were found in lung samples." (PMID 34830758, 2021). "VHL is mutated in several cancers, but in melanoma mutations are rare." (PMID 38902533, 2024). "We first looked at an extended list of high-risk genes predisposing to melanoma (ACD, CDKN2A, CDK4, POT1, TERF2IP, and TERT) or RCC (CDKN2B, FH, FLCN, MET, PBRM1, PTEN, SDHs, TSCs, and VHL) or both (BAP1 and MITF)." (PMID 34067022, 2021). "We reported here that VHL is the E3 ligase for CIP2A in melanoma." (PMID 39399646, 2024). "Nevertheless, the loss of VHL was shown to increase HIF levels and expression of genes with HRE elements, e.g., VEGF, GLUT-1, ALD-A, and PFK-L, which are associated with a glycolytic phenotype, when melanoma cells were injected into mice." (PMID 28806730, 2017). "Additionally, loss of VHL was connected to increased skin vascularization, which is known to contribute to growth and angiogenesis, potentially through iNOS and EPO signaling, in many cancers including melanoma." (PMID 28806730, 2017). "Among them, six E3 ligases were highly expressed in melanoma cells: BRCA1, CUL3, RNF4, UBR5, CHIP, and von Hippel‒Lindau (VHL)." (PMID 39399646, 2024). "Hence, even though VHL is not frequently mutated in melanoma, low expression and lack of protein could promote the glycolytic phenotype we predicted for melanoma." (PMID 28806730, 2017). "VHL-Mb24 reduced ERK phosphorylation levels following EGF stimulation of NRAS expressing RASless HEK cells but did not affect ERK phosphorylation levels in NRASQ61L-mutant WM-1366 melanoma cells." (PMID 39379700, 2024). "Additionally, von Hippel‒Lindau (VHL) is the endogenous E3 ligase for CIP2A, and PF enhances the interaction between VHL and CIP2A, promoting the ubiquitin‒proteasome degradation of CIP2A, thereby inhibiting melanoma growth and metastasis." (PMID 39399646, 2024). "Knockdown of VHL in melanoma cells led to increased CIP2A protein expression, suggesting that VHL may be the natural E3 ligase for CIP2A and that PF might enhance the interaction between VHL and CIP2A, thereby increasing CIP2A instability and degradation." (PMID 39399646, 2024). "Our discoveries that manipulations of CXCR7 have minimal impact on HIF-1α mRNA level and VHL expression, whereas significantly modulate HIF-1α accumulation in the presence of the proteasome inhibitor MG132, suggest that CXCR7 promotes HIF-1α translation in melanoma cells." (PMID 30804329, 2019). "Thus, the experimental data supported the predicted role of IDH2 and the absence of VHL protein supported the glycolytic and low oxygen phenotype predicted for melanoma." (PMID 28806730, 2017). "Moreover, the von Hippel-Lindau tumor suppressor (VHL) protein, whose loss is associated with non-hypoxic HIF-stabilization, reductive carboxylation, and promotion of glycolysis, was uniformly absent in melanoma." (PMID 28806730, 2017). "In further support of the distinctive tissue patterns of the melanoma cell lines, VHL was not detectable at protein levels in skin cancer or melanoma, and only low RNA expression levels were detected in melanoma cell lines that were not part of the NCI-60 panel." (PMID 28806730, 2017). "Hence, the lack of VHL emerged as a prominent feature of normal skin and melanoma." (PMID 28806730, 2017).